TRAJ49 (T cell receptor alpha joining 49)
Gene: T-cell receptor joining (J) gene on chromosome 14 (22,489,488 to 22,489,543, forward strand). Ensembl gene ENSG00000211840.
Diseases named in the same sentence as TRAJ49 in open-access papers:
TRAJ49 is named in the same sentence as 2 diseases in open-access papers, as found by Europe PMC text mining. Sharing a sentence is not in itself a finding about the gene and the disease. The quoted sentences say what the papers report.
infection (1 paper, 2025). The state of being infected such as from the introduction of a foreign agent such as serum, vaccine, antigenic substance or organism. "Several common TRA and TRB pairs, such as TRAV1-2/TRAJ33, TRAV21/TRAJ49, TRBV6-4/TRBD2/TRBJ2-3, and TRBV5-1/TRBD1/TRBJ2-7, were consistently detected from the primary infection (PI) through the convalescent phase (HC) and into the reinfection phase (RI)." (PMID 41209021, 2025).
TRAJ49 also shares sentences with these, for which no sentence is quoted: Allergy (1 paper).